FBN1 (fibrillin 1)
Diseases named in the same sentence as FBN1 in open-access papers (continued):
Sharing a sentence is not in itself a finding about the gene and the disease.
Marfan syndrome (continued). "The archetype of genetic aortic disease is Marfan syndrome, caused by pathogenic variants in the Fibrillin-1 gene." (PMID 34336739, 2021). "Medial deterioration leading to thoracic aortic aneurysms arises from multiple causes, chief among them mutations to the gene that encodes fibrillin-1 and leads to Marfan syndrome." (PMID 34977201, 2021). "Marfan syndrome (MFS) is a hereditary connective tissue disease caused by heterozygous mutations in the fibrillin-1 gene (FBN1) located on chromosome 15q21.1." (PMID 34828442, 2021). "We found the homozygous FBN1 variant p.(Arg954His) in a boy with typical features of Marfan syndrome." (PMID 33436942, 2021). "Marfan syndrome (MFS) is an autosomal dominant connective tissue disease caused by a mutation in fibrillin-1, which leads to systemic diseases with various phenotypes." (PMID 34456753, 2021). "In comparison, FBN1 pathogenic variants are essentially fully penetrant in individuals with Marfan syndrome." (PMID 34600884, 2021). "Mutations in the gene encoding FBN1 have been identified in cattle with rupture and dissection of the thoracic aorta, similar to that seen in human Marfan syndrome." (PMID 34607531, 2021). "Marfan syndrome (MFS) is an autosomal dominant disorder caused by mutations in the FBN1 gene, which codes for fibrillin‐1, a major component of microfibrils and elastic fibers." (PMID 34042309, 2021). "The patient with Marfan syndrome was from a Marfan syndrome family, with a thin body habitus, long limbs, and an FBN1 gene mutation." (PMID 34118978, 2021). "Both gene variations of FBN1 and SMAD4 are easily misinterpreted as Marfan syndrome caused by FBN1 and misdiagnosed." (PMID 34236823, 2021). "Marfan syndrome is an autosomal dominant condition of connective tissue, associated in 90% of cases with mutations on the fibrillin-1 (FBN1) gene." (PMID 34946804, 2021). "The most common disease linked to FBN1 mutations is the Marfan syndrome, an autosomal dominant multi-systemic disorder of connective tissue." (PMID 33469097, 2021). "Mutations within the 47 epidermal growth factor-like (EGF) repeats of FBN1 cause autosomal dominant disorders including Marfan Syndrome, which is characterized by disrupted TGF-β signaling." (PMID 34411563, 2021). "It has been reported that in CHD and related complications, the c.3964 + 1G > T mutation in intron 32 of gene FBN1 can contribute to Marfan syndrome." (PMID 34765091, 2021). "Although multiple studies have shown FBN1 mutations as the cause of Marfan syndrome (MFS), which is further associated with increased risk of tumourigenesis, very little is known about the role of FBN1 mutations in cancer." (PMID 34386072, 2021). "The mutation in FBN1 was responsible for Marfan’s syndrome and other disorders of connective tissues." (PMID 35095892, 2021). "The Marfan syndrome (MFS) is an autosomal dominant systemic disorder of connective tissue caused by an altered mutation in the Fibrillin-1 gene (FBN1)." (PMID 34106976, 2021). "Mutations in FBN1 disrupt the formation of microfibrils, ultimately leading to a disease phenotype; either Marfan syndrome or another type-1 fibrillinopathy." (PMID 33801742, 2021). "Marfan syndrome (MFS) is an inherited connective tissue disorder that is often caused by the mutation of fibrillin 1 (Fbn1) and the consequent extracellular matrix (ECM) degeneration." (PMID 34769168, 2021). "Mutations in fibrillin 1 are predominantly associated with Marfan Syndrome, and lead to connective tissue abnormalities and cardiovascular complications." (PMID 31914925, 2020). "Mutations in the FBN1 gene cause Marfan syndrome, a genetic connective tissue disorder characterized by aortic aneurysms and dissections." (PMID 32486169, 2020). "A known pathogenic variant in FBN1 (c.3712G>A, p.Asp1238Asn) was detected and a certain diagnosis of Marfan syndrome (MIM# 154700) was given." (PMID 32730690, 2020).
Marfan syndrome (continued). "Marfan syndrome (MFS) is an inherited connective tissue disease that mainly involves Fibrillin‐1 (FBN1) mutations and aortic manifestations." (PMID 31830381, 2020). "A heterozygous FBN1 mutation in mice accelerates vascular aging and eventually leads to aortic manifestations, resembling those of Marfan syndrome." (PMID 32486169, 2020). "Further knowledge has been gained from examination of corneal structure in the fibrillin-1 mgΔloxPneo mouse model for Marfan syndrome, in which the mutant FBN1 allele creates a truncated fibrillin-1 monomer." (PMID 32173378, 2020). "Marfan syndrome (MFS) is a systemic disorder of connective tissue caused by pathogenic variants in the fibrillin-1 (FBN1) gene." (PMID 33028885, 2020). "Previous studies have demonstrated that deleterious FBN1 mutations causing Marfan syndrome result in upregulated endogenous transforming growth factor β (TGF‐β) receptor signaling (Andelfinger, Loeys, & Dietz, 2016)." (PMID 31774634, 2020). "Marfan syndrome (MFS) is a connective tissue disorder caused by mutations in FBN1 gene encoding for the extracellular matrix (ECM) glycoprotein fibrillin-1, a structural component of 10–12-nm-sized calcium-binding microfibrils." (PMID 32961817, 2020). "Trio ES through the UDN found a pathogenic, de novo, heterozygous nonsense variant in FBN1 (c.871G>T, p.E219X) resulting in a certain diagnosis of Marfan syndrome (MIM# 154700)." (PMID 32730690, 2020). "Although both types of FBN1 mutations are important for understanding the pathogenic mechanisms of Marfan syndrome, disease onset of our FBN1 KO cloned pig model was caused by haploinsufficiency." (PMID 32210272, 2020). "In this study, we examined the regulation of FBN1 in porcine Marfan syndrome model, focusing on DNA methylation patterns distinguishable as wild-type (WT) and FBN1 null (KO) alleles in heterozygous cells." (PMID 32210272, 2020). "We observed four additional variants (rs11070641, rs4775760, rs363832 and rs140605) in FBN1 to be associated with high standing/sitting height ratio, a characteristic feature often observed in Marfan syndrome." (PMID 33226994, 2020). "Particularly concerning, therefore, is that loss of constituents such as fibrillin-1, as in Marfan syndrome, can compromise both elastic fiber integrity and mechanosensing." (PMID 33079926, 2020). "Marfan syndrome (MFS) is a systemic disorder of connective tissue caused by mutations in the fibrillin-1 (FBN1) gene." (PMID 32006082, 2020). "FBN-1: Marfan syndrome is a well-known heritable disorder caused by a mutation in fibrillin-1 affecting different organs and systems, with TAA and aortic dissection the main cause of morbidity and mortality in these patients." (PMID 32260370, 2020). "In Marfan’s syndrome, which is characterized by a fibrillin-1 gene mutation and excessive TGF-β leading to the development of aortic arch aneurysm and dissection, it is not clear if targeting the renin–angiotensin system can be beneficial." (PMID 32664652, 2020). "In this study, we found a heterozygous c.3217G > T (p.Glu1073*) nonsense variant in the FBN1 gene, which eventually led to Marfan syndrome in a Chinese family." (PMID 33087052, 2020). "Marfan syndrome (MFS) is a connective tissue disorder caused by mutations in the FBN1 gene that produces wide disease phenotypic variability." (PMID 33230159, 2020). "Marfan syndrome, a rare hereditary connective tissue disorder caused by mutations in fibrillin-1, can affect many organ systems, especially the cardiovascular system." (PMID 33256748, 2020). "For example, we show that a commonly found variant in FBN1 was associated with high standing/sitting height ratio and reduced body fat percentage as observed in individuals with Marfan syndrome." (PMID 33226994, 2020). "Perhaps the most well studied is the Fbn1C1039G mouse that harbors a cysteine to glycine knock-in mutation in Fibrillin-1 and recapitulates features of Marfan Syndrome." (PMID 32824919, 2020).
Marfan syndrome (continued). "Endothelium dysfunction is an important contributor to Marfan syndrome, caused by mutations in the FBN1 gene." (PMID 32486169, 2020). "The considerable number of non-FBN1 mutations identified suggests that gene panel testing should be preferred instead of single gene screening in patients with the suspicion of Marfan syndrome and related disorders." (PMID 33059708, 2020). "Marfan syndrome is an autosomal dominant connective tissue disease caused by mutations in the Fbn-1 gene that encodes the glycoprotein fibrillin-1, the major structural component of microfibrils." (PMID 32173378, 2020). "A defect in the Fibrillin-1 gene is also the underlying mutation in Marfan’s syndrome, which is associated with increased prevalence of aortic aneurysms." (PMID 32707846, 2020). "For example, variants in the FBN1 gene are responsible for most cases of marfan syndrome, but the phenotypic effect of alleles of FBN1 is modified by other genes such as gMod-M1-9 and COL4A1." (PMID 32664512, 2020). "For example, Marfan syndrome is a heritable connective tissue disorder characterized by mutations in the FBN1 gene and manifested in development of thoracic aortic aneurysm." (PMID 31871214, 2020). "Marfan syndrome is often caused by mutations in the fibrillin-1 gene, resulting in abnormalities of fibrillin metabolism and altered elastic microfibril and ECM assembly in the aorta in most patients." (PMID 33228202, 2020). "Variants in FBN1 are associated with Marfan syndrome, an autosomal dominant connective tissue disorder characterized by ocular, skeletal, and cardiovascular abnormalities, including aortic dilatation and cardiac valve regurgitation." (PMID 32379818, 2020). "According to an OMIM report, the patient’s phenotype highly agrees with the symptoms of an autosomal dominant disorder known as Marfan syndrome caused by variants on the FBN1 gene located on 15q21.1." (PMID 33087052, 2020). "Increased applanation tonometry derived AIx has been reported in patients with Marfan syndrom, a genetic connective tissue disorder due to mutation in the fibrillin 1 gene." (PMID 32933483, 2020). "Mutation in this gene has been identified as the cause of congenital contractural arachnodactyly (CCA), a disorder phenotypically similar to Marfan syndrome (caused by mutation in the related gene FBN1)." (PMID 32216834, 2020). "Taken together with the results of this study, disease onset and severity of haploinsufficient Marfan syndrome involves DNA hypermethylation on the WT allele within the FBN1 CpG island shore that results in decreased functional FBN1 mRNA levels." (PMID 32210272, 2020). "For ectopia lentis, genetic testing is particularly helpful in confirming or excluding FBN1-associated disorders (including Marfan syndrome)." (PMID 31848469, 2020). "Marfan syndrome (MFS) is a highly variable genetic connective tissue disorder caused by mutations in the calcium binding extracellular matrix glycoprotein fibrillin-1." (PMID 33033378, 2020). "Altogether, only 17 genes were primarily identified in relation to cervical insufficiency, with six being syndromic, i.e. COL1A1 and COL3A1 causing EDS; FBN1 causing Marfan syndrome; ZMPSTE24 and LMNA causing restrictive dermopathy; and MATR3 causing myopathy." (PMID 32214361, 2020). "While FBN1 mutations and subsequent increases in TGFβ signaling cause the initial onset of mitral valve pathogenesis in Marfan Syndrome, the mechanisms that further drive progressive myxomatous degeneration to the point of end-stage prolapse are not known." (PMID 32824919, 2020). "A next-generation sequencing panel containing 15 genes including FBN1 was used to determine the underlying pathogenic variants of Marfan syndrome." (PMID 32939518, 2020). "On the other hand, according to previous reports of diseases that can coincide with CS, there was one male case with micropenis who was reported as demonstrating Marfan syndrome with an FBN1 gene variant (Chiu, Thakuria, & Agrawal, 2010)." (PMID 31060112, 2019).
Marfan syndrome (continued). "Fibrillin is a major component of microfibrils in extracellular matrices, and variants in the fibrillin gene (FBN1) can cause Marfan syndrome, which has many features including myopia and risk of retinal detachment." (PMID 30568244, 2019). "In patients suffering from Marfan syndrome (MFS) the FBN1 mutation is inherited autosomal dominant with considerable phenotypical variability." (PMID 31427685, 2019). "Marfan’s syndrome (MFS) is a systemic disorder of connective tissue caused by mutations in the extracellular matrix protein fibrillin-1; its prevalence has been estimated as 1 in 5–10,000 individuals." (PMID 31065451, 2019). "Mutations in FBN1 underlie Marfan syndrome [MFS; Mendelian Inheritance in Man (MIM): 154700] and the autosomal dominant form of Weill-Marchesani syndrome (AD WMS; MIM: 608328), conditions that severely affect the eye." (PMID 30642872, 2019). "The causal gene in Marfan syndrome is the FBN1 gene with pathogenic variants identified in more than 90% of Marfan phenotypes." (PMID 31795342, 2019). "These proteins play key roles in elastogenesis and mutations in LTBP and fibulin genes, in common with Marfan syndrome causing fibrillin-1 mutations, can manifest as pathologies in multiple organ systems." (PMID 30016650, 2019). "Marfan’s syndrome (MFS) is a systemic disorder of connective tissue caused by mutations in the extracellular matrix protein fibrillin-1." (PMID 31065451, 2019). "Marfan syndrome (MFS) is an autosomal dominant genetic disorder caused by mutations in the FBN1 gene." (PMID 30677223, 2019). "This latest nosology for the first time also put weight on the identification of pathogenic variants in the Fibrillin1 gene (FBN1) which is the causal gene in Marfan syndrome." (PMID 31795342, 2019). "Marfan syndrome (MFS) is a rare connective tissue disorder mainly due to mutations in the FBN1 gene." (PMID 30754709, 2019). "The responsible gene for Marfan syndrome has been identified as FBN1, which encodes the major microfibrillar protein, fibrillin-1 that play a crucial role in the composition of elastic system fibers." (PMID 31065451, 2019). "Marfan syndrome (MFS) is an autosomal dominant genetic disorder of connective tissue caused most frequently by mutations in the fibrillin-1 gene." (PMID 30417312, 2019). "Pathogenic variants in FBN1 cause autosomal dominant Marfan syndrome but can also be found in patients presenting with apparently isolated features of Marfan syndrome." (PMID 30485715, 2019). "Well-known examples are Marfan syndrome (MFS) with a mutation in the extracellular matrix protein Fibrillin-1, Loeys-Dietz syndrome (LDS) with mutations in genes including the TGF-β-receptors 1 and 2, and SMAD3." (PMID 31683995, 2019). "For 84 (93.3%) of the 90 patients with FBN-1 variants, it was possible to give a definite diagnosis of Marfan syndrome in accordance with modified Ghent criteria." (PMID 29357934, 2018). "Mutations in Fbn1 most commonly cause Marfan syndrome (MFS) with life-threatening cardiovascular defects, bone overgrowth, joint laxity/contractures and ectopia lentis, caused by elastic fibre defects and/or growth factor dysregulation." (PMID 30060141, 2018). "In diseases caused by microfibril defects, elastic fiber networks can be disrupted, as in the aorta of mice with a mutation in the fibrillin-1 gene (Fbn1) used as a model of Marfan syndrome." (PMID 30406200, 2018). "FBN1, a gene that is thought to be causative of vascular damage and whose mutations have been previously detected only in relation to Marfan syndrome, was selected by Jeppesen and colleagues as their research focus." (PMID 29495593, 2018). "There has been growing evidence of intrinsic myocardial dysfunction in patients with Marfan syndrome (MFS) caused by pathogenic variants in the FBN1 gene." (PMID 29717556, 2018).
Marfan syndrome (continued). "Mutations in FBN1 are the major cause of Marfan syndrome, an autosomal dominant disorder characterized by multiple manifestations in the ocular, skeletal, and cardiovascular systems." (PMID 29760442, 2018). "The importance of fibrillin-1 in the function of tissues is further highlighted by fibrillin-1 mutations that cause a number of heritable connective tissue disorders termed fibrillinopathies, such as Marfan syndrome (MFS) and Weill–Marchesani syndrome (WMS)." (PMID 30120953, 2018). "Expression of miR-29a/b/c were all shown to be increased in fibullin-4-deficient mice, a model of TAA, and in fibrillin-1-deficient mice, a model of Marfan syndrome." (PMID 28425970, 2017). "When abnormal Fbn-1 was first identified as the cause of Marfan syndrome in 1991, it was believed that the coding mutations resulted in a structural weakness of microfibrils, leading to arterial wall “weakness” and the syndrome's vascular manifestations." (PMID 28993736, 2017). "Marfan syndrome is an autosomal dominant genetic disorder that affects connective tissue and is caused by mutations in the fibrillin 1 gene present at chromosome 15." (PMID 29430308, 2017). "Mutations in the FBN1 gene have been identified in 70–93% of persons who meet the diagnostic criteria for Marfan syndrome with more than 1,000 unique FBN1 mutations observed in this population." (PMID 28116311, 2017). "Marfan syndrome (MFS) is an autosomal dominant hereditary disorder of connective tissue that results from mutations in the gene for fibrillin 1 (Fbn1), the major constitutive element of extracellular microfibrils." (PMID 29187826, 2017). "Marfan syndrome is the result of mutations in the FBN1 gene on chromosome 15, which encodes fibrillin-1, an extracellular matrix (ECM) protein that forms microfibrils and controls vessel elasticity." (PMID 28116311, 2017). "Marfan syndrome (MFS) involves a deficiency of the structural extracellular matrix component fibrillin-1 and overactivation of the transforming growth factor-β (TGF-β) signalling pathway." (PMID 29042385, 2017). "Fibrillin-1 (FBN1) mutations associated with Marfan syndrome lead to an increase in transforming growth factor β (TGF-β) activation in connective tissues resulting in pathogenic changes including aortic dilatation and dissection." (PMID 28669633, 2017). "Marfan syndrome (MFS) is a pleiotropic connective tissue disease caused by a deficiency of the structural extracellular matrix component fibrillin-1 (FBN-1)." (PMID 29042385, 2017). "Marfan syndrome, caused by loss-of-function FBN1 mutations, can result in aortic dilatation and dissection, as well as pathological changes to the skeleton and the eye." (PMID 28669633, 2017). "Marfan’s syndrome is caused by mutations in the gene encoding fibrillin-1, which regulates the transforming growth factor beta (TGF-beta) signaling pathway." (PMID 27646033, 2016). "Marfan syndrome (MFS) is an autosomal-dominant disorder of connective tissue caused by mutations in the fibrillin-1 (FBN1) gene." (PMID 27824871, 2016). "Marfan syndrome (MFS) is a variable autosomal dominant disorder of the connective tissue caused by mutations in the fibrillin-1 gene on chromosome 15 encoding the microfibrillar protein fibrillin-1." (PMID 28050285, 2016). "Early morbidity and mortality in patients with Marfan syndrome (MFS) -a connective tissue disease caused by mutations in fibrillin-1 gene- are mainly caused by aorta aneurysm and rupture." (PMID 27003297, 2016). "Previous reports have described that mutations in the fibrillin-1 (FBN1) gene, on chromosome 15q21.1, have been found to result in Marfan syndrome, a dominantly inherited disorder characterized by clinically skeletal, ocular and cardiovascular abnormalities." (PMID 27761171, 2016). "For example, missense mutation of conserved amino acids in cbEGFs of fibrillin 1 (FBN1) are causative for Marfan syndrome due to Ca2+-dependent misfolding of the protein." (PMID 27815347, 2016).